Y_RNA (Y RNA )
Gene: Miscellaneous RNA gene on chromosome 3 (53,290,640 to 53,290,751, forward strand). Ensembl gene ENSG00000274967.
Homologues: Orthologues: chimpanzee Y_RNA (97% identical), macaque Y_RNA (91% identical). Paralogues in human: Y_RNA (82% identical), RNY1P5 (81% identical), Y_RNA (80% identical), Y_RNA (79% identical), Y_RNA (78% identical), Y_RNA (77% identical), RNY1P1 (76% identical), Y_RNA (76% identical), RNY1P6 (75% identical), Y_RNA (75% identical), Y_RNA (74% identical), RNY1 (73% identical), and 93 more.